RNU6-371P (RNA, U6 small nuclear 371, pseudogene)
Gene: Small nuclear RNA gene on chromosome 1 (62,298,149 to 62,298,256, reverse strand). Ensembl gene ENSG00000201153.
Homologues: Orthologues: macaque U6 (94% identical), chimpanzee U6 (92% identical), pig U6 (86% identical), guinea pig U6 (55% identical). Paralogues in human: RNU6-744P (87% identical), RNU6-742P (86% identical), RNU6-1060P (85% identical), RNU6-1125P (85% identical), RNU6-116P (85% identical), RNU6-1175P (85% identical), RNU6-11P (85% identical), RNU6-132P (85% identical), RNU6-15P (85% identical), RNU6-188P (85% identical), RNU6-37P (85% identical), RNU6-609P (85% identical), and 1286 more.